MYC (MYC proto-oncogene, bHLH transcription factor)
Diseases named in the same sentence as MYC in open-access papers (continued):
Sharing a sentence is not in itself a finding about the gene and the disease.
blood cancer (32 papers, 2011 to 2025). "This review mainly focuses on the effects of EBF1, PAX5, and MYC on B cell development and their association with hematologic neoplasms." (PMID 38318177, 2024). "Common oncogenic drivers of blood cancer, like MYC or BCR-ABL1, are linked to centrosome amplification in experimental models, and in the latter case, p210 BCR-ABL1 is reportedly a centrosome-associated protein in chronic myeloid leukemia cells." (PMID 38552015, 2024). "The proto-oncogene c-MYC has been associated with tumorigenesis, especially in hematological neoplasms." (PMID 37627164, 2023). "In short, as pivotal TFs in B cell development, the abnormalities of EBF1, PAX5, and MYC result in hematologic tumors." (PMID 38318177, 2024). "As concerns MYC gene amplifications, they are found in both hematopoietic and non-hematopoietic tumors." (PMID 39482742, 2024). "Due to the great potential of ARQ531 in overcoming resistance to Ibrutinib, it has entered phase I clinical trials for various MYC-involved hematological neoplasms [NCT03162536]." (PMID 34372899, 2021). "MYC is considered a master gene and is one of the most well-studied genes in hematologic neoplasms and solid tumors." (PMID 34830760, 2021). "In other types of blood cancers, specific miRNAs involved in the regulation of MYC gene expression have also been discovered." (PMID 34440124, 2021). "The first demonstrations of MYC oncogenic capabilities in hematological neoplasms were seen in Eμ-MYC transgenic mice." (PMID 34372899, 2021). "Several studies have identified lncRNAs regulating c-MYC expression and c-MYC regulated lncRNAs in different blood cancers and have unveiled new mechanisms how these RNA molecules act." (PMID 33134177, 2020). "Treatment with recombinant 1746c27_Omomyc (cargo 4) induced a dose-dependent decrease in cell viability in MYC-dependent blood cancer cell lines and T47D cells in the presence of sera." (PMID 30135446, 2018). "Here we analyzed the role of A1 in MYC as well as ABL kinase-driven blood cancer in mice, employing in vivo RNAi." (PMID 27694901, 2017). "Given that the aberrant expression and function of EBF1, PAX5, and MYC contribute to hematologic neoplasms, therapies targeting them may shed light on these diseases." (PMID 38318177, 2024). "In addition to NUT carcinoma, GSK525762 has also been tested on a vast spectrum of hematological neoplasms in order to indirectly inhibit the master oncoprotein MYC." (PMID 34372899, 2021). "Although the understanding of MYC’s regulatory role controlling lncRNA expression and how MYC itself is controlled by lncRNA in blood cancers is still at the beginning, an intriguing picture emerges indicating that c-MYC may execute part of its oncogenic function through lncRNAs." (PMID 33134177, 2020). "Hence, A1 should be considered as a putative drug target in MYC-driven blood cancer." (PMID 27694901, 2017). "For example, the proviral enhancer of the avian leucosis virus (ALV), which induces hematopoietic tumors, can be integrated upstream of the MYC gene leading to c-Myc overexpression." (PMID 39482742, 2024). "It has also been observed to decrease the proliferation and survival of cell lines derived from hematological neoplasms by decreasing the expression of crucial transcription factors such as NK-κB, STAT1, or MYC." (PMID 34975915, 2021). "Rearrangements of MYC or ABL proto-oncogenes lead to deregulated expression of key-regulators of cell cycle and cell survival, thereby constituting important drivers of blood cancer." (PMID 27694901, 2017). "Subsequently, the 5th edition of the WHO classification of hematological neoplasms (WHO-HAEM5) has adopted this separator for translocations which involve conventional genes and IG and TR loci in hematological neoplasms, also italicizing these genes and IG and TR loci (e.g IGH::MYC and IGH::CCND1)." (PMID 38664547, 2024). "Notably, TRIB3 knockdown decreases MYC expression in most blood cancer cells but not in U937 AML cells or bjab BL cells." (PMID 33298911, 2020).
blood cancer (continued). "Consequently, to develop new and effective therapies for blood cancers, it is essential to target c-MYC, specifically that c-MYC inhibitors have not yet received clinical approval." (PMID 37627164, 2023).
hematological cancers (32 papers, 2013 to 2025). "MYC alterations in hematological cancers differ from the ones observed in solid tumors, e.g., the former predominantly present MYC translocations and point mutations, while the latter are mostly characterized by MYC amplifications." (PMID 41008653, 2025). "Genetic rearrangements involving MYC locus are a predominant mechanism leading to MYC overexpression in multiple hematological cancers." (PMID 41008653, 2025). "Upregulation of interferon alpha and gamma response and downregulation of c-MYC target genes, in function of c-MYC reduced expression (monitored in all the hematopoietic neoplasms tested), represent the most significant modulated pathways." (PMID 36536122, 2023). "In solid tumors, the MYC locus at 8q24 is often amplified, whereas in hematological cancers, MYC dysregulation is often a result of chromosomal translocations." (PMID 33494394, 2021). "Selective inhibitors of BET proteins exhibit potent anti-proliferative activity in a number of hematologic cancer models, in part through suppression of the MYC oncogene and downstream Myc-driven pathways." (PMID 24009722, 2013). "Of note, a diagnostic c-MYC immunohistochemical staining has been developed for hematological cancers, and this could potentially support the use of c-MYC in future clinical studies of TAK-243 or newer UBA1 inhibitors in TNBC." (PMID 36712364, 2022). "Conversely, in the 19 hematological cancer cell lines, we did not observe higher sensitivity associated with MYC alterations (amplified, driver‐mutated, translocated; Fig EV2B and C)." (PMID 29769258, 2018). "MYC is deeply involved in the pathogenesis of several hematological cancers." (PMID 25925570, 2015). "Chromosomal translocations in the MYC locus is very commun in haematopoietic cancers." (PMID 23717612, 2013).
CNS tumors (10 papers, 2018 to 2025). "Adult CNS tumours have high CDK6 amplification, 10q loss, and 17q gain, whereas paediatric cases have a high frequency and high specificity of 3q and 4q losses across MYC/MYCN oncogene amplification, suggesting variations in the chromosomal abnormalities between adult and paediatric CNS tumours." (PMID 39439908, 2024). "Well-characterized TEAD targets in non-CNS tumors include CTGF, Cyr61, MYC, CCNE1, AREG, and EGFR44,54,55." (PMID 30275445, 2018).
gastrointestinal tumor (10 papers, 2008 to 2025). "Following quantification, IGF1Rβ protein was on average 2.1-fold higher (p<0.001) and c-MYC was about 2.5-fold higher (p<0.02) in Ptp4a3-null relative to wildtype colon tumors." (PMID 23555575, 2013). "Importantly, our observations uncover a novel ubiquitination cascade composed of UBA6, UBE2Z, and FBXW7 that may regulate the degradation of the squamocin‐induced EZH2/MYC axis in pan‐gastrointestinal tumors." (PMID 39823459, 2025).
neurodegenerative disease (10 papers, 2015 to 2025). A disorder of the central nervous system characterized by gradual and progressive loss of neural tissue and neurologic function. "Instead, together with the five upstream signalling factors (IGF1, BDNF, ZAP70, MYC, and cyclosporin A) they could help uncover the molecular mechanisms mediating AD or different neurodegenerative diseases." (PMID 26059363, 2015). "This aligns with studies showing upregulation of MYC proteins in reactive astrocytes across neurodegenerative diseases, contributing to astrogliosis independent of neuronal death." (PMID 40656638, 2025).
neurological disorders (4 papers, 2021 to 2025). "Further research is required to comprehensively understand the intricacies of miR-34b-mediated regulation of the MYC gene in the context of brain injury and neurological disorders." (PMID 39129166, 2025). "The gene MYC was found to be differentially methylated in the current study and was previously reported to be differentially expressed in neurological disorders." (PMID 34260616, 2021).
myopathy (3 papers, 2018 to 2024). A disease of the muscle in which the muscle fibers do not function properly. "This also suggests that possibly different pathways are regulated by MYC in different tissues in HIBM myopathy, which needs further investigation." (PMID 34825065, 2021). "Deficiency of the MYC target gene, phosphoglycerate kinase 1 (PGK1), from genetic mutations, may cause myopathy." (PMID 39457090, 2024).
colonic polyps (2 papers, 2023 to 2026). "The MYC oncogene (on chromosome 8) and other immunoregulatory genes on chromosome 8 may contribute to aberrant epithelial regeneration, immune dysregulation, and cytokine‐driven intestinal ulcer formation." (PMID 41522796, 2026). "In our study, we found that β-catenin levels increased concurrently with its pro-proliferative targets MYC and MMP-7 in the Hnf1A98V polyps, while CDX2 levels were depressed in the colonic polyps but not in the adjacent tissue." (PMID 37219942, 2023).
inflammation (2 papers, 2019 to 2022). Aberrant reaction of the microcirculation characterized by movement of fluid and leukocytes from the blood into extravascular tissues. "Moreover, high zinc concentrations impaired nuclear expression of the metabolic transcription factor MYC, prevented Th1 and Th2 differentiation in vitro and reduced Th1 autoimmune central nervous system (CNS) inflammation and Th2 asthmatic airway inflammation induced by house dust mites in vivo." (PMID 35121767, 2022).
mitochondrial disease (2 papers, 2023). "The most robust evidence for potential pathological role of MYC induction in mitochondrial disease comes from our studies on the CIII-deficient Bcs1lp.S78G mice, as reviewed above." (PMID 37731815, 2023). "Additional circumstantial evidence for the involvement of MYC in mitochondrial disease pathogenesis came from a study assessing the regulation of the mitochondrial integrated stress response by the mitokine FGF21 in mitochondrial cardiomyopathy." (PMID 37731815, 2023). "Elucidation of MYC’s beneficial adaptive and potentially pathological roles in mitochondrial diseases requires in vivo modulation of MYC." (PMID 37731815, 2023). "Albeit not widely acknowledged thus far, several cell and mouse models of mitochondrial disease show upregulation of MYC and/or its typical transcriptional signatures." (PMID 37731815, 2023). "Our findings urge further studies on the role of c-MYC, aberrant cell proliferation, and accumulation of senescent cells in mitochondrial diseases." (PMID 37095097, 2023). "Our results connect primary OXPHOS deficiency to genomic instability and progeroid pathogenesis and suggest that targeting c-MYC and aberrant cell proliferation may be therapeutic in mitochondrial diseases." (PMID 37095097, 2023). "If MYC-driven DNA damage and cellular senescence occur also as a consequence of other mitochondrial disease mutations than those causing severe CIII deficiency, understanding the role of MYC could enable several novel therapeutic options." (PMID 37731815, 2023). "Here, we argue that MYC could be a functionally important player in mitochondrial diseases, hoping to stimulate researchers of mitochondrial medicine and physiology to study MYC in their models." (PMID 37731815, 2023). "What are the consequences of MYC upregulation in tissues affected by mitochondrial disease?" (PMID 37731815, 2023). "It is an interesting question whether MYC upregulation has pathological and perhaps targetable roles in less severe mitochondrial diseases and their experimental models." (PMID 37731815, 2023). "To understand why and how MYC might be needed in response to mitochondrial dysfunction, such as in mitochondrial diseases, we will take a brief look at what is known about how MYC regulates some key mitochondria-related functions." (PMID 37731815, 2023). "Current evidence for MYC upregulation in models of mitochondrial disease or dysfunction." (PMID 37731815, 2023). "In the next section, we shall turn to what is currently known about MYC in experimental OXPHOS dysfunction and mitochondrial disease models." (PMID 37731815, 2023).
connective tissue disorder (1 paper, 2020). A disease involving the connective tissue. "Among the top disease subnetworks designated by IPA, MYC CNVs were associated with skeletal/muscular disorders and RAD21 CNVs were associated with connective tissue disorders." (PMID 32859084, 2020).
neuromuscular disease (1 paper, 2021). "The findings of our study suggest that V727M GNE mutation may alter GNE and MYC protein interaction at the C terminal domain, thus could be leading to altered MYC role in regulating neuromuscular disease-associated gene expression, as well as the expression of ST genes in cells." (PMID 34825065, 2021).
MYC also shares sentences with these, for which no sentence is quoted: cardiovascular diseases (9 papers); skin cancer (9); cervical squamous cell carcinoma (7); B-Cell Acute Lymphocytic Leukemia (5); bacterial infections (5); Hepatic steatosis (5); metabolic disease (5); renal failure (5); viral hepatitis (5); Hepatitis C (4); inflammatory bowel disease (4); Lewis lung carcinoma (4); mucosal (4); nervous system tumours (4); papillary lung adenocarcinoma (4); pemphigus (4); schizophrenia (4); serous adenocarcinoma (4); teratocarcinoma (4); tongue squamous cell carcinoma (4); adrenocortical carcinoma (3); amyotrophic lateral sclerosis (3); basal cell carcinoma (3); benign tumors (3); brain ischemia (3); central nervous system lymphoma (3); cervical intraepithelial neoplasia (3); colon (3); gastric adenoma (3); infectious disease (3).
A further 326 diseases each share a sentence with MYC in 3 papers or fewer.